LSM5 (LSM5 homolog, U6 small nuclear RNA and mRNA degradation associated)
Description:
Plays a role in pre-mRNA splicing as component of the U4/U6-U5 tri-snRNP complex that is involved in spliceosome assembly, and as component of the precatalytic spliceosome (spliceosome B complex). The heptameric LSM2-8 complex binds specifically to the 3'-terminal U-tract of U6 snRNA.
Synonyms: YER146W
Tractability: Small molecule: a structure with a bound ligand is known. PROTAC: ubiquitination databases record sites on it; its protein half-life has been measured.
Gene: Protein-coding gene on chromosome 7 (32,485,338 to 32,495,283, reverse strand). Ensembl gene ENSG00000106355.
Subcellular location: Nucleus
Pathways (Reactome):
Metabolism of RNA: mRNA Splicing - Major Pathway; mRNA decay by 5' to 3' exoribonuclease
Gene Ontology:
Molecular function: protein binding; protein heterodimerization activity; RNA binding
Biological process: mRNA catabolic process; mRNA splicing, via spliceosome; deadenylation-dependent decapping of nuclear-transcribed mRNA; mRNA processing; spliceosomal snRNP assembly; spliceosomal tri-snRNP complex assembly
Cellular component: cytoplasm; Lsm2-8 complex; nucleus; precatalytic spliceosome; spliceosomal complex; U2-type precatalytic spliceosome; U4/U6 x U5 tri-snRNP complex; cytosol; Lsm1-7-Pat1 complex; nucleoplasm; U4/U6 snRNP; U4atac/U6atac snRNP; U4atac/U6atac x U5 tri-snRNP complex; U6 snRNP; U6atac snRNP
Genetic constraint (gnomAD): Loss-of-function variants: 2 observed, 4.2 expected, observed/expected ratio (o/e) 0.48, 90% interval 0.19 to 1.44. That is too few expected variants to judge how well the gene tolerates losing a copy. Missense variants: 29 observed, 32.46 expected, observed/expected ratio (o/e) 0.89, 90% interval 0.66 to 1.22. Synonymous variants: 13 observed, 13.57 expected, observed/expected ratio (o/e) 0.96, 90% interval 0.62 to 1.52.
Homologues: Orthologues: chimpanzee LSM5 (100% identical), dog LSM5 (100% identical), guinea pig LSM5 (100% identical), mouse Lsm5 (100% identical), pig LSM5 (100% identical), rat Lsm5 (97% identical), zebrafish lsm5 (95% identical), macaque LSM5 (85% identical), Drosophila melanogaster CG6610 (78% identical), Caenorhabditis elegans lsm-5 (74% identical).
Diseases named in the same sentence as LSM5 in open-access papers:
LSM5 is named in the same sentence as 15 diseases in open-access papers, as found by Europe PMC text mining. Sharing a sentence is not in itself a finding about the gene and the disease. The quoted sentences say what the papers report.
colon adenocarcinoma (1 paper, 2022). "Importantly, LSM5 and DACF4 upregulation in resistant patient samples seem to be unfavorable factors in colon adenocarcinoma patients, leading to a higher mortality rate." (PMID 35885025, 2022).
Infertility (1 paper, 2021). "Down-regulation of U6 snRNA-associated Sm-like protein LSm5 could facilitate the disruption of normal cellular functions, resulting in infertility." (PMID 34311720, 2021).
lung carcinoma (1 paper, 2022). "At present, the mechanism of action of LSM4 and LSM5 in lung cancer has not been reported." (PMID 36389112, 2022).
non-small cell lung carcinoma (1 paper, 2023). A group of at least three distinct histological types of lung cancer, including non-small cell squamous cell carcinoma, adenocarcinoma, and large cell carcinoma. "A study revealed that non-small-cell lung cancer (NSCLC) cell lines are particularly sensitive to the loss of the LSM2-8 protein complex (especially LSM2, LSM4, and LSM5)." (PMID 37312186, 2023).
cancer (2 papers, 2020 to 2024). A tumor composed of atypical neoplastic, often pleomorphic cells that invade other tissues. "Aberrant splicing is observed in many types of cancers, so changes in LSM5 expression can point to the presence of cancer changes." (PMID 39000458, 2024).
tumor (2 papers, 2021 to 2023). "Most importantly, to elucidate the certain role of LSM5, 7 and 8, we conducted qPCR in 13 GC patients that had paired tumor and normal tissues." (PMID 37007092, 2023). "In this study, we have firstly identified LSM5 and LSM8 as favourable biomarkers related to 5-FU chemotherapy resistance and investigated their relationship with tumor microenvironment and immune therapy in GC patients." (PMID 37007092, 2023). "Additionally, with the analysis of tumor immunity and chemoresistance, we were the first to demonstrate that LSM5 and LSM8 were tightly correlated with chemoresistance and immune infiltration, and thus might be potential biomarkers for predictions of survival in GC patients." (PMID 37007092, 2023).
LSM5 also shares sentences with these, for which no sentence is quoted: adenoid cystic carcinoma (1 paper); atherosclerosis (1); breast carcinoma (1); colon cancer (1); esophageal carcinoma (1); lung adenocarcinoma (1); Lynch syndrome (1); stomach adenocarcinoma (1); uterine corpus endometrial carcinoma (1).